MYCN (MYCN proto-oncogene, bHLH transcription factor)
Diseases named in the same sentence as MYCN in open-access papers (continued):
Sharing a sentence is not in itself a finding about the gene and the disease.
neuroblastoma (continued). "SH-EP cells were incubated with EVs purified from TET21-N neuroblastoma cells in MYCN-off or MYCN-on conditions." (PMID 34847775, 2021). "The impact of NTRK1 activation on the proteome and the phosphoproteome was delineated using the MYCN-amplified neuroblastoma cell line, IMR5." (PMID 34771457, 2021). "A previous study has concluded that MYCN-amplified neuroblastoma cells have defective G1-arrest despite induction of p21." (PMID 34827693, 2021). "This combination was validated in a diverse panel of neuroblastoma cell lines and in vivo, including a patient-derived xenograft mouse model of MYCN-amplified neuroblastoma." (PMID 34681760, 2021). "Taken together these data showed that MYCN-induced increases in neuroblastoma cell viability and proliferation were, in part, dependent on ALYREF." (PMID 33767157, 2021). "We show strong co-operativity between ALYREF and MYCN from transgenic models of neuroblastoma in vitro and in vivo." (PMID 33767157, 2021). "Taken together, these experiments suggest that EVs secreted by MYCN-positive cells increase the proliferation rates and metabolic activity of stromal and MYCN single-copy neuroblastoma cells by inducing a Warburg switch." (PMID 34847775, 2021). "Treatment of MYCN-amplified neuroblastoma organoids resulted in organoid disintegration, decreased cell viability, and increased apoptotic cell death." (PMID 34118691, 2021). "The A-NB94 trial was the first in Austria to apply a risk-adapted treatment strategy for children with neuroblastoma considering INSS stage, age, and MYCN amplification status." (PMID 33540616, 2021). "These datasets include MYCN-amplified and non-MYCN amplified neuroblastoma models representing one relapse, two primary tumors, and 10 metastases." (PMID 34118691, 2021). "Depletion of PRMT1 in this report reduced the expression of MYCN and cell viability in primary neuroblastoma tumors." (PMID 33440687, 2021). "Specifically, overexpression of TrkA and TrkC is a favourable prognostic biomarker in neuroblastoma, while TrkB is often expressed in neuroblastomas with MYCN amplification, which per se is an unfavourable biological factor in these patients." (PMID 33620682, 2021). "In a transgenic MYCN neuroblastoma zebrafish model, tumors develop with increased penetrance when one allele of both arid1aa and arid1ab are absent, indicating a haploinsufficient effect." (PMID 34885007, 2021). "Combined ATR and Aurora-A inhibition demonstrated selective efficacy in a mouse model of MYCN-derived neuroblastoma, leading to permanent eradication of tumors in a subset of mice." (PMID 34201047, 2021). "S5A), in particular, the two most common neuroblastoma predisposition genes, ALK and PHOX2B, and the cancer gene MYCN, somatic amplification of which is a key adverse marker used clinically for neuroblastoma risk stratification." (PMID 33547074, 2021). "In neuroblastomas, MYCN amplification is conducive to reduce immune infiltration and neuroblastoma cells have been shown to secrete macrovesicles able to stimulate the production of pro-tumourigenic signals by bone marrow stromal cells." (PMID 34847775, 2021). "Among the glycolytic enzymes enriched in the EVs of MYCN-expressing neuroblastoma cells, we identified hexokinase II and PKM2." (PMID 34847775, 2021). "Cluster 3 and 4 neuroblastomas expressed higher levels of the GSK-J4 signature, and were enriched with high-risk, high-stage and MYCN-amplified tumors." (PMID 34893606, 2021). "Splicing abnormalities are present in both human neuroblastomas and a mouse model of MYCN-driven neuroblastoma." (PMID 34788094, 2021). "Our analyses revealed a strong effect of miRNAs of the miR-17 seed family and potential involvement of let-7 family members in controlling MYCN expression in neuroblastoma." (PMID 34026620, 2021). "Cyclin-dependent kinase 4 (CDK4) is one of the putative transcriptional targets of MYC and is highly expressed in neuroblastomas with MYCN amplification." (PMID 34069817, 2021).
neuroblastoma (continued). "MYCN was a stronger transcriptional regulator of the ODC1 promoter containing the G allele, and preferentially bound the G allele over the A. Two neuroblastoma cohorts were used to investigate the clinical impact of the SNP." (PMID 33918978, 2021). "MYCN amplification occurs in ~20% of neuroblastomas and has been established as a key driver of an aggressive and chemoresistant tumour phenotype, frequently observed in high-risk neuroblastoma and predictive of poor patient outcome." (PMID 34064704, 2021). "In MYCN-amplified neuroblastoma, 147 selective candidate gene dependencies were identified, providing potential therapeutic insight for this difficult to treat childhood cancers." (PMID 34663432, 2021). "Ornithine decarboxylase (ODC1), a critical regulatory enzyme in polyamine biosynthesis, is a direct transcriptional target of MYCN, amplification of which is a powerful marker of aggressive neuroblastoma." (PMID 33918978, 2021). "Together these data highlight an unexpected vulnerability of MYCN protein to unanchored polyubiquitin chain levels in neuroblastoma cells and suggest a novel therapeutic strategy." (PMID 33658627, 2021). "MYCN was first discovered in neuroblastoma and later also found to be overexpressed in retinoblastoma, brain tumors, leukemia, neuro-endocrine prostate cancers and pancreatic cancer." (PMID 34262099, 2021). "Our findings emphasize the potency of post-transcriptional regulation of MYCN in neuroblastoma and unravel new avenues to pursue inhibition of this potent oncogene." (PMID 34026620, 2021). "Our results demonstrate that inhibition of fatty acid synthesis induces differentiation in neuroblastoma independently of MYCN-status, providing approaches for development of more specific fatty acid synthesis inhibitors that can be used in the clinic." (PMID 33659885, 2021). "This was investigated for MYCN-targeting miRNAs upregulated in MNA neuroblastoma, like miR-17-92 cluster miRNAs, or substantially expressed like the let-7 miRNA family." (PMID 34026620, 2021). "Somatic amplification of the MYCN gene is found in 20% of all neuroblastoma patients, which results in higher MYCN protein levels." (PMID 34769149, 2021). "Subsequent functional analyses suggested that ARID1A and ARID1B were haploinsufficient tumor suppressor genes in MYCN-driven neuroblastoma." (PMID 34796286, 2021). "It has been reported that neuroblastoma cell differentiation requires a timely regulation of MYCN expression, with early overexpression, followed by downregulation." (PMID 33659885, 2021). "Curcumin also inhibits transcriptional activation of the motility, angiogenesis, and metastasis-stimulating factor autotaxin (ENPP2) in human neuroblastomas where the MYC gene paralogue MYCN is amplified." (PMID 33937075, 2021). "As expected, we were able to detect neuroblastoma-relevant copy number alterations, including the exact determination of MYCN copy number." (PMID 34442335, 2021). "The TH-MYCN mouse model represents a highly penetrant transgenic model of neuroblastoma that expresses high levels of human MYCN in the developing sympathetic tissues using a conditional rat tyrosine hydroxylase promoter." (PMID 34638267, 2021). "The nanoparticle delivers a siRNA molecule that silences the proto‐oncogene MYCN as a neuroblastoma tumor‐specific target." (PMID 35712226, 2021). "Subsequently, other transcriptionally addicted malignancies, including MYCN-amplified neuroblastoma and MYC/MYCL-amplified SCLC showed also sensitivity to CDK7 inhibition." (PMID 33686962, 2021). "We next investigated if ibrutinib can reduce tumor growth in MYCN amplified neuroblastoma tumor model." (PMID 33669187, 2021). "Several groups have reported that MYCN and ALK gain-of-function mutations, either in locus or overexpressed, cooperate to drive transformation, and result in increased neuroblastoma penetrance in both cell line—mouse and zebrafish—models." (PMID 34885007, 2021).
neuroblastoma (continued). "Our findings demonstrate that inhibition of de novo fatty acid synthesis is a promising pharmacological intervention strategy for the treatment of neuroblastoma independently of MYCN-status." (PMID 33659885, 2021). "Here we show that the deubiquitinase, USP5, has an important role in maintaining MYCN stability through effects on unanchored polyubiquitin levels in neuroblastoma cells." (PMID 33658627, 2021). "MYCN is amplified in 20–25% of neuroblastomas, and its amplification correlates with a poorer prognosis in these patients." (PMID 34539578, 2021). "To this end, we have investigated two RNA-binding proteins (RBPs), previously reported to control MYCN expression in neuroblastoma, ELAVL4 (HuD) and IGF2BP1." (PMID 34026620, 2021). "MYCN amplification was the first identified clinically relevant molecular biomarker for neuroblastoma, and remains a strong single predictor for unfavorable outcome." (PMID 34202325, 2021). "In particular, the CBP/p300 inhibitor C646 shows promise as a targeted MYCN amplified neuroblastoma therapeutic." (PMID 33968920, 2021). "ALK amplification has also been reported in neuroblastoma almost invariably together with amplification of the adjacent gene MYCN, with possible synergistic effects in driving cell growth and survival." (PMID 34063424, 2021). "Pharmacological inhibition of MRE11, through encapsulation of the mirin drug in nanoparticles, induces accumulation of RS, impairment of tumor growth and apoptosis in MYCN-amplified neuroblastoma xenografts in vivo." (PMID 34201047, 2021). "RTNs with siRNA against MYCN (a member of the Myc family of transcription factors) in mice with MYCN‐amplified neuroblastoma tumors show significant retardation of xenograft tumor growth and enhanced survival." (PMID 35712226, 2021). "Independent of MYCN amplification, MYCN expression levels and MYCN regulated signature are also correlated with the unfavorable outcomes of neuroblastoma." (PMID 34116676, 2021). "Next, whole cell extracts of MYCN-amplified neuroblastoma cells IMR32 were prepared to detect oligomers of endogenous NCYM." (PMID 34497756, 2021). "A panel of MYCN-amplified neuroblastoma organoids was employed to run a high-throughput screen, selecting the inhibitor of kinesin spindle protein, ARRY-520, as an agent to cause reduced organoid viability." (PMID 33808071, 2021). "Neuroblastoma differentiation requires an initial increase in MYCN protein expression followed by a reduction." (PMID 33659885, 2021). "It is worth noting that the neuroblastoma mouse model driven by MYCN/ALKF1174L and C-MYC had even better outcomes following indisulam treatment than the PDX and cell line–generated models, which are conducted in immunodeficient mice." (PMID 34788094, 2021). "In this study, we describe ALYREF as a key regulator of MYCN turnover and neuroblastoma tumorigenesis." (PMID 33767157, 2021). "Amplification of the MYCN oncogene from 2p24 occurs in 25% of neuroblastoma patients, and is a well‐recognized marker of tumor aggressiveness." (PMID 33767157, 2021). "Together, this provides strong evidence that IGF2BP1 is a potent miRNA antagonist upregulating MYCN mRNA and protein in neuroblastoma." (PMID 34026620, 2021). "MYCN amplification is frequently observed in neuroblastoma primary tumors and cell lines, and MYCN over-expression has been shown to drive tumorigenesis in a transgenic mouse model when placed under the control of the TH promoter." (PMID 34200747, 2021). "The MYCN proto-oncogene is deregulated in many cancers, most notably in neuroblastoma, where MYCN gene amplification identifies a clinical subset with very poor prognosis." (PMID 33562123, 2021). "Using a MYCN-amplified neuroblastoma PDX model, we observed that rigosertib can delay tumor growth in vivo, accompanied by an increase in apoptotic cells." (PMID 34118691, 2021).
neuroblastoma (continued). "We show that neuroblastoma cells expressing high levels of MYCN are especially sensitive to ATR inhibition, and that this is due to MYCN-increased RS." (PMID 34944835, 2021). "This is achieved in neuroblastomas with MYCN gene amplification because endogenous cis-regulatory elements included in the MYCN amplicon are selectively activated by the adrenergic CRC." (PMID 34669465, 2021). "have identified seven miRNAs whose expressions have been increased by MYCN in vitro and are over-expressed in primary neuroblastomas that harbor MYCN amplification." (PMID 33718173, 2021). "Combination therapy with an HDAC inhibitor (SAHA) and a novel pyridobenzimidazole (SE486-11) bound and inactivated USP5 with potent inhibition of tumorigenicity as a novel therapeutic approach for the treatment of MYCN-driven neuroblastoma." (PMID 33658627, 2021). "Repeated administration of low-dose topotecan leads to DNA damage and induced senescence in both MYCN-amplified neuroblastoma cells and in vivo in neuroblastoma xenografts, together with tumor regression." (PMID 34066606, 2021). "MYCN is a recognized biomarker in neuroblastomas, but little is known about the expression of MYCN in less aggressive brain tumors." (PMID 33430425, 2021). "They showed that deletion of the zebrafish ARID1A homologs, arid1aa and arid1ab, resulted in accelerated onset and increased penetrance of MYCN-driven neuroblastoma in a transgenic zebrafish model." (PMID 34885007, 2021). "Experimental demonstration for the critical role of MYCN in neuroblastoma was from MYCN transgenic mouse models in which neuroblastoma spontaneously developed." (PMID 32087738, 2020). "We found that MYC transcription factor was positively correlated with the MYCN amplification in neuroblastoma in TARGET dataset." (PMID 32593299, 2020). "Another candidate co-regulator is TEAD4, which drives the MYCN-induced transcription network in MYCN-amplified neuroblastomas, although we were unable to detect TEAD4 in a MYCN-transduced fetal retina." (PMID 33425720, 2020). "We previously found that miR-506-3p down-regulated MYCN expression in three neuroblastoma cell lines." (PMID 32087738, 2020). "The data demonstrated that miR-98 was highly involved in miR-98/MYCN axis-mediated inhibition of neuroblastoma progression by RNA N6-methyladenosine modification." (PMID 32788584, 2020). "Despite its central role in neuroblastoma biology, the epigenetic regulation of MYCN is incompletely understood." (PMID 33199677, 2020). "MYCi975 is yet to be tested in brain tumor models but decreased MYCN protein levels in a neuroblastoma cell line." (PMID 33585252, 2020). "Quantitative PCR-based detection of MYCN amplifications in peripheral blood from neuroblastoma patients was proven feasible in 2002, before the concept of cancer liquid biopsies was established." (PMID 31897843, 2020). "Another major pathway active in ETMRs is the v-myc myelocytomatosis viral related oncogene, neuroblastoma derived (MYCN) pathway." (PMID 32601913, 2020). "MYCN amplification is present in ~30–40% of high-grade neuroblastoma patients and is a poor prognostic factor." (PMID 32547946, 2020). "Our findings altogether suggest that the interplay network formed by PLAGL2, MYCN and miR-506-3p is an important mechanism in regulating neuroblastoma cell fate, determining neuroblastoma prognosis, and mediating the therapeutic function of retinoic acid." (PMID 32087738, 2020). "In this case, LIN28B, or LIN28B mutant that is unable to inhibit let-7 processing, increases the penetrance of MYCN-induced neuroblastoma, potentiates the invasion and migration of transformed sympathetic neuroblasts, and drives distant metastases in vivo." (PMID 33054808, 2020).
neuroblastoma (continued). "Except MYC, transcription factor E2F1 was also positively enriched in MYCN amplified neuroblastoma tissues in GSE19274 and GSE85047 datasets." (PMID 32593299, 2020). "We obtained tumor gene expression data from six stage 4, MYCN-NA neuroblastoma samples from the UCSC Treehouse gene expression compendium." (PMID 32275708, 2020). "Dysregulated expression of the transcription factor MYCN is frequently detected in nervous system tumors such as childhood neuroblastoma." (PMID 33585251, 2020). "This analysis identified 931 genes within the MYCN-NA neuroblastoma cohort with a multimodal expression distribution." (PMID 32275708, 2020). "A model summarizing how miR‐15a, miR‐15b, and miR‐16 suppress tumor progression in neuroblastoma by targeting MYCN." (PMID 31637848, 2020). "A genome-wide, drop-out shRNA screen carried out in our laboratory has identified CKS1B as a potential therapeutic target gene in MYCN-amplified neuroblastoma by inducing synthetic lethality." (PMID 31900399, 2020). "These associations persisted in case‐case analyses comparing MYCN‐amplified to MYCN‐unamplified neuroblastoma." (PMID 32945147, 2020). "In neuroblastoma, Mdm2 can acts as a tumor promoting factor as seen in Mdm2 haploinsufficient (Mdm2+/-) MYCN transgenic mice which show a decreased tumor incidence, latency, and reduced tumor growth." (PMID 33585251, 2020). "All-trans retinoic acids have been used for neuroblastoma therapy for decades by inhibiting the expression of MYCN and inducing the neuronal differentiation of neuroblastoma cells." (PMID 33614505, 2020). "Using our analysis, we find that the highest scoring MYCN peptide (TVRPKNAAL) has predicted binding to 9 HLA alleles, representing 58.1% of the population, and we expect analysis of more neuroblastoma tumor specimens will validate this prediction." (PMID 32256484, 2020). "Aurora-A, a member of the Aurora kinase family, is identified in an shRNA screen of genes that are highly expressed in MYCN-amplified neuroblastoma cells and contributes to the stabilization of N-MYC." (PMID 33614505, 2020). "Further studies have additionally shown that in neuroblastoma cells MYCN targets a separate E-box location and, similarly to c-MYC, augments transcription of SKP211." (PMID 31900399, 2020). "MYC, E2F1 transcription factors and ribosome signaling pathway were significantly enriched in neuroblastoma patients with MYCN amplification." (PMID 32593299, 2020). "Neuroblastoma cell differentiation is triggered by certain signals, including repression of MYCN expression, overexpression of tumor suppressive miRNAs, and pharmacological concentrations of differentiation agent retinoic acid (RA)." (PMID 32087738, 2020). "In neuroblastoma, MYCN amplification is used as a prognostic marker and is indicative of a high-risk disease." (PMID 31900399, 2020). "We performed the 3D colony forming assay after 24 h glutamine deprivation combined with different doses of X-rays in the two non-MYCN-amplified neuroblastoma cell lines, SH-SY5Y and SK-N-AS, stably overexpressing MYCN." (PMID 32483461, 2020). "For example, lncRNA MYCNOS upregulates MYCN expression in neuroblastoma by recruiting CTCF to promoter region of this gene to induce chromatin remodeling." (PMID 32719429, 2020). "In agreement with previous reports, LGALS3BP was expressed in neuroblastoma cell lines, independently of MYCN amplification." (PMID 33076448, 2020). "Our data showed that glutamine deprivation led to a downregulation of MycN and c-Myc expression at both mRNA and protein levels in neuroblastoma cells harbouring MYCN amplification or high c-Myc expression respectively." (PMID 32483461, 2020). "One study reported that silencing the long noncoding RNA MYCNOS1 results in reduced cell proliferation of MYCN-amplified neuroblastoma and rhabdomyosarcoma." (PMID 33270844, 2020).